TROAP (trophinin associated protein)
Diseases named in the same sentence as TROAP in open-access papers (continued):
Sharing a sentence is not in itself a finding about the gene and the disease.
ovarian carcinoma (4 papers, 2019 to 2025). A malignant neoplasm originating from the surface ovarian epithelium. "TROAP is highly expressed in ovarian cancer cell lines and positively associated with poor prognosis in ovarian cancer; thus, TROAP is regarded as a prognostic marker in ovarian cancer." (PMID 31198787, 2019). "METTL14-catalyzed m6A modification is markedly reduced in ovarian carcinoma tissues, and reinstatement of METTL14 expression may attenuate ovarian cancer cell proliferative capacity by repressing trophinin-associated protein (TROAP) levels." (PMID 40986143, 2025). "In conclusion, METTL14 overexpression decreased ovarian cancer proliferation by inhibition of TROAP expression via an m6A RNA methylation-dependent mechanism." (PMID 35251990, 2022). "Further in vivo and in vitro experiments confirmed that METTL14 is a negative regulator of ovarian cancer cell proliferation via TROAP expression and that m6A RNA methylation regulates TROAP mRNA stability." (PMID 35251990, 2022). "Restoration of METTL14 expression suppresses ovarian cancer cell proliferation by inhibition of TROAP expression." (PMID 35251990, 2022). "We further demonstrated that METTL14 inhibited the expression of TROAP via the m6A RNA modification in ovarian cancer cells, which also inhibited cell proliferation by suppress cyclin D1, survivin, and p-AKT." (PMID 35251990, 2022). "We transfected ovarian cancer SKOV-3 and A2780 cells with a METTL14 expression vector or Trophinin associated protein (TROAP) siRNA." (PMID 35251990, 2022). "In summary, the current study delineates that METTL14 negatively regulates TROAP expression in an m6A RNA methylation-dependent manner and that its expression is reduced in ovarian cancer and promotes cancer cell proliferation." (PMID 35251990, 2022). "Altogether, these data suggest that METTL14 functions as a negative regulator of TROAP in ovarian cancer cells and tissues." (PMID 35251990, 2022). "Thus, we performed qRT-PCR and wester blotting and observed a dramatic increased TROAP expression in ovarian cancer tissues." (PMID 35251990, 2022). "Taken together, these data suggest that METTL14 may function as a negative regulator of ovarian cancer cell proliferation via inhibition of TROAP and its downstream targets." (PMID 35251990, 2022). "We then transfected exogenous TROAP into the METTL14-overexpressing ovarian cancer cells." (PMID 35251990, 2022). "To further verify whether METTL14-induced downregulation of TROAP expression is dependent on m6A mRNA methylation in ovarian cancer tissues and cells, we assessed the m6A methylation rate in ovarian cancer cells after transfection with the METTL14 expression vector." (PMID 35251990, 2022).
glioblastoma (3 papers, 2021 to 2023). The most malignant astrocytic tumor (WHO grade IV). "Conversely, most gene biomarkers were negatively correlated with TROAP expression in THYM, testicular germ cell tumors, glioblastoma multiforme, NB, and lung squamous cell carcinoma." (PMID 36419876, 2022).
lung carcinoma (3 papers, 2019 to 2023). "TROAP expression was significantly higher in most cancers, which was in accordance with previous research on lung cancer and LIHC, and with our confirmed results using qRT-PCR and Western blot analysis." (PMID 36419876, 2022).
colon cancer (2 papers, 2023). "Similarly, TROAP is upregulated in other malignant tumors, such as liver, ovarian, prostate, and colon cancers." (PMID 37298609, 2023).
gallbladder cancer (2 papers, 2019 to 2021). "Furthermore, TROAP was known to be highly expressed in gallbladder cancer tissue and promoted tumor invasion and metastasis." (PMID 34077623, 2021).
lung adenocarcinoma (2 papers, 2022 to 2025). A carcinoma that arises from the lung and is characterized by the presence of malignant glandular epithelial cells. "The other work documented that KLF13 restrained epithelial–mesenchymal transition of lung adenocarcinoma cells through inhibiting TROAP transcription." (PMID 41410190, 2025). "TROAP gene CNV was positively correlated with OS in kidney renal clear cell carcinoma (KIRC), uterine corpus endometrial carcinoma (UCEC), breast invasive carcinoma(BRCA), and lung adenocarcinoma (LUAD)." (PMID 36419876, 2022).
ovarian tumor (2 papers, 2022 to 2024). "Further investigation revealed that METTL14 reduced the stability of TROAP mRNA, which consequently arrested ovarian tumor cells at the G1 phase of the cell cycle and inhibited their proliferation." (PMID 35251990, 2022). "Overexpression of METTL14 can reduce the mRNA stability of target gene by mediating m6A methylation modification which will reduce the expression of trophinin-associated protein (TROAP), thus placing ovarian tumor cells in the G1 phase of the cell cycle and inhibiting their proliferation." (PMID 38343637, 2024).
pancreatic adenocarcinoma (2 papers, 2021 to 2022). "Upregulated TROAP predicts the poor OS and DFS in patients with adrenocortical carcinoma, kidney renal clear cell carcinoma, pancreatic adenocarcinoma, skin cutaneous melanoma and HCC." (PMID 33500384, 2021).
testicular germ cell tumor (2 papers, 2019 to 2022). A germ cell tumor arising from the testis. "Many types of cancer express TROAP and human chorionic gonadotrophin (hCG), a marker of trophoblasts; for example, TROAP expression is observed in all cases of testicular germ cell tumors with lung metastasis." (PMID 31198787, 2019).
breast invasive carcinoma (1 paper, 2022). "Subsequently, TROAP expression showed a significant positive association with TMB in 16 of 37 cancers, among which kidney chromophobe (KICH) had the highest correlation coefficient and breast invasive carcinoma had the lowest correlation coefficient." (PMID 36419876, 2022).
chronic lymphocytic leukemia (1 paper, 2022). "TROAP expression increased in almost all cancer cell lines, with the highest level observed in small cell lung carcinoma and the lowest expression in chronic lymphocytic leukemia." (PMID 36419876, 2022).
lentivirus infection (1 paper, 2023). Virus diseases caused by the Lentivirus genus. "After 3 days of shRNA lentivirus infection, the mRNA and protein expression of TROAP in 786-O and ACHN cells in the experimental group were inhibited." (PMID 37298609, 2023). "The invasion (transwell) assay showed that the invasion and metastasis ability of 786-O and ACHN cells in the experimental group was significantly inhibited after 3 days of shRNA lentivirus infection, suggesting a significant correlation with TROAP." (PMID 37298609, 2023).
melanoma (1 paper, 2023). A malignant, usually aggressive tumor composed of atypical, neoplastic melanocytes. "Further clinical investigations are imperative to elucidate the molecular mechanisms underlying the role of TROAP in melanoma progression." (PMID 37127623, 2023). "An AUC value of 0.679 suggests that TROAP has an excellent diagnostic value for melanoma." (PMID 37127623, 2023). "A range of experiments studying cell functions indicated that the ability of melanoma cells to grow, proliferate, invade and migrate were declined by knocking down TROAP." (PMID 37127623, 2023). "The validation of mRNA expression levels of TROAP was performed, which indicated a significant increase in TROAP expression in our clinical melanoma specimens compared with paired normal tissues." (PMID 37127623, 2023). "Meanwhile, the same tendency of TROAP expression is observed in melanoma cell lines and normal skin cell HaCaT." (PMID 37127623, 2023). "In conclusion, TROAP was found to play a significant role in melanoma proliferation, invasion, and metastasis, thus supporting the findings of the bioinformatics study." (PMID 37127623, 2023). "We selected two cases of TROAP in melanoma with IHC pictures and found TROAP was positively expressed in skin melanocytes and melanoma." (PMID 37127623, 2023). "The findings from the in vitro and in vivo experiments indicated that the viability, proliferation, and invasion ability of melanoma cells were drastically decreased after the knockdown of TROAP." (PMID 37127623, 2023). "We acquired immunohistochemical staining data from the HPA database in order to investigate the protein expression levels of TROAP in melanoma tissues and surrounding tissues." (PMID 37127623, 2023). "The role of TROAP in melanoma was also confirmed by cell and animal assays, which may provide useful insight into melanoma treatment strategies." (PMID 37127623, 2023). "Finally, six LLPS-related genes (MLKL, PARVA, PKP1, PSME1, RNF114, and TROAP) constitute the prognostic model and predicted clinical outcomes in melanoma patients." (PMID 37127623, 2023). "The TROAP expression in melanoma cells was dramatically higher than that in normal cells." (PMID 37127623, 2023). "PKP1 and TROAP were commonly amplified in melanoma patients." (PMID 37127623, 2023). "Nevertheless, only a few researchers have focused on the prognostic role of TROAP in melanoma." (PMID 37127623, 2023). "This implied that TROAP may exert a potentially pivotal influence on the proliferation of melanoma cell lines." (PMID 37127623, 2023). "Importantly, the function of the key gene TROAP in melanoma was validated by in vitro experiments." (PMID 37127623, 2023). "Finally, the role of key gene TROAP in melanoma was validated by in vitro and in vivo experiments." (PMID 37127623, 2023). "Therefore, TROAP can become a potential target in melanoma treatment." (PMID 37127623, 2023). "Through LASSO regression, the following six genes were specifically identified to have an irreplaceable prognostic effect on melanoma patients: MLKL, PARVA, PKP1, PSME1, RNF114, and TROAP." (PMID 37127623, 2023). "Melanoma samples from the TCGA and GTEX integrated datasets demonstrated a high level of TROAP expression." (PMID 37127623, 2023). "The proliferation ability of TROAP on melanoma cells was evaluated by CCK-8 and EdU assay, the results from which indicate that compared to the control group, the viability and EdU positive cell ratio declined in A375 and WM-115 cells transfected with sh-TROAP." (PMID 37127623, 2023).
metastatic disease (1 paper, 2025). "Among the nominated hub genes, CDCA8 and TROAP consistently emerged as markers of aggressive disease biology, demonstrating associations with subsequent metastasis in initially non-metastatic patients and with adverse survival among patients presenting with metastatic disease." (PMID 41008819, 2025). "CDCA8 and TROAP emerge as candidate prognostic biomarkers, linking postoperative metastatic progression in an initially M0 cohort with survival in metastatic disease." (PMID 41008819, 2025).
myocardial infarction (1 paper, 2021). Gross necrosis of the myocardium, as a result of interruption of the blood supply to the area, as in coronary thrombosis. "Trophinin associated protein (TROAP) is shown to be involved in myocardial infarction, thus, its role in LVNC could also be important." (PMID 34859074, 2021).
ovarian adenocarcinoma (1 paper, 2025). An adenocarcinoma that arises from the ovary. "TROAP exhibits oncogenic properties in CRC and ovarian adenocarcinoma, where its overexpression drives malignant progression and tumor aggressiveness." (PMID 41614789, 2025).
serous ovarian adenocarcinoma (1 paper, 2017). "Among other genes, TROAP was reported only in four papers and one paper reported its detection in serous ovarian adenocarcinoma." (PMID 28489584, 2017).
soft tissue sarcoma (1 paper, 2023). A malignant neoplasm arising from muscle tissue, adipose tissue, blood vessels, fibrous tissue, or other supportive tissues excluding the bones. "Herein, we comprehensively explored the molecular characteristics and prognostic value of TROAP in soft tissue sarcoma (STS), revealing its relationship with the immune microenvironment and chemotherapy." (PMID 37731946, 2023).
tumor (22 papers, 2016 to 2025). "ECM-related integrin, beta-like 1 (ITGBL1), cadherin 11 (CDH11) and trophinin-associated protein (TROAP) were upregulated, perhaps reflecting a reorganisation of the tumour microenvironment that is permissive of invasion and metastasis." (PMID 38124114, 2023). "Trophinin‐associated protein (TROAP) is augmented in a variety of tumors and can affect tumor proliferation." (PMID 37731946, 2023). "Based on the crucial role of the tumor immune microenvironment in malignancy progression and occurrence, the association between tumor immune infiltration and TROAP in STS was further investigated." (PMID 37731946, 2023). "Demonstrating that TROAP expression is closely associated with immune infiltration of tumor cells, affecting patient prognosis, and providing new targets for the development of immunosuppressive agents." (PMID 36419876, 2022). "The upregulation of TROAP is considered to be associated with poor prognosis of cancer cohort, and its dysregulated expression can inhibit the proliferation and metastasis ability of tumor cells, hinting that the TROAP is closely associated with the malignant behavior of tumor." (PMID 37731946, 2023). "Additionally, we examined possible associations between TROAP expression and tumor-infiltrating lymphocytes (TILs) and immune subtypes in the TME." (PMID 36419876, 2022). "Furthermore, we found a correlation between TROAP expression and genomic and post-transcriptional alterations in various tumors, including tumor mutation burden, and microsatellite instability." (PMID 36419876, 2022). "Finally, the specific mechanism of the TROAP expression change in tumor cells that causes the tumor immune microenvironment status, the change of drug sensitivity, and the possible molecular mechanism in drug sensitivity change need further clarification in future research." (PMID 37731946, 2023). "Thus, TROAP plays a significant role in promoting tumor growth and metastasis and may be a potential diagnostic biomarker for BC." (PMID 31198787, 2019). "Xenograft tumor experiments in nude mice confirmed our suspicion that tumor growth was slowed in the TROAP knockdown group." (PMID 37298609, 2023). "Based on The Cancer Genome Atlas (TCGA), Gene expression Omnibus (GEO), and other tumor public databases, we explored the expression and prognosis significance of TROAP in STS." (PMID 37731946, 2023). "By combining tumor tissue data in the TCGA database with normal tissue data in the Genotype‐Tissue Expression (GTEx) database, our observation was that TROAP indicates a trend of significant upregulation in STS." (PMID 37731946, 2023). "Compared with the shCtrl group, the volume and weight of the tumors derived from shTROAP KIRC cells were significantly reduced, suggesting that TROAP downregulation inhibits KIRC tumor growth in vivo." (PMID 37298609, 2023). "TROAP can affect tumor progression through various pathways; for example, it can promote disease progression through the Wnt3/survival protein signaling pathway in prostate cancer." (PMID 37298609, 2023). "TROAP activates the Wnt/β-catenin pathway and upregulates the expression of its downstream targets to play a tumor-promoting role." (PMID 36588901, 2022). "G1/S Progression search yielded two studies, one of which identified an important role of TROAP in cell cycle regulation and enhanced tumour progression." (PMID 35269752, 2022). "Further single-cell analysis of tumor immunity using the TISCH database revealed a notably positive correlation between TROAP and Proliferating T cells in 26 tumors." (PMID 36419876, 2022). "Further single-cell analysis of tumor immunity using the TISCH database uncovered a significant positive correlation between TROAP and Proliferating T cells in 26 tumors." (PMID 36419876, 2022). "Our analysis of drug databases revealed that TROAP expression is related to multiple anti-tumor drug sensitivity." (PMID 36419876, 2022).
tumor (continued). "Among the 44 tumor types, TROAP was significantly correlated with stromal scores in 30 cancer types and immune scores in 27 cancers." (PMID 36419876, 2022). "The mRNA and protein expression of METTL14 were negatively correlated with TROAP in the tumor tissues dissected from the nude mice." (PMID 35251990, 2022). "Inversely, one study has proved that TROAP played an inhibitory role on tumor growth and metastasis in HCC10." (PMID 33500384, 2021). "While the expression of these proteins and TROAP‐induced tumor‐promoting effects (proliferation, migration and invasion) would be significantly reversed by silencing Axin2 or β‐Catenin." (PMID 34077623, 2021). "Combination of cisplatin with an inhibitor of DYRK1 AZ191 effectively inhibited tumor growth in mouse model for HCC cells with high level of TROAP." (PMID 33500384, 2021). "TROAP expression was significantly increased in HCC tissues compared with adjacent non-tumor liver tissues." (PMID 33500384, 2021). "IHC staining also showed the higher expression of TROAP in HCC tissue than that in corresponding non-tumor liver tissue." (PMID 33500384, 2021). "Trophinin-associated protein (TROAP) has been shown to be overexpressed and promotes tumor progression in some tumors." (PMID 33692939, 2020). "According to previous findings, a high TROAP expression predicts poor prognosis or tumor progression in ovarian and breast cancers and in hepatocellular carcinoma." (PMID 33692939, 2020). "TROAP has been shown to promote some tumor progressions, such as those of breast and colorectal cancers." (PMID 33692939, 2020). "The results showed that FAM64A and TROAP were significantly upregulated in tumor tissues (p value < 0.0001)." (PMID 28489584, 2017). "Mechanistically, CDCA8 and TROAP converge on pathways of mitotic fidelity and chromosomal segregation, processes that may promote chromosomal instability, tumor evolution, and therapeutic resistance." (PMID 41008819, 2025). "Collectively, it can be preliminarily inferred that the TROAP expression change in tumor cells may result in the tumor immune status dysregulation, which may count for the poor prognosis of STS patients." (PMID 37731946, 2023). "The tumor weight and volume were also significantly reduced due to TROAP silencing." (PMID 37127623, 2023). "Consequently, we further investigated the correlation between TROAP and tumor immune infiltration, trying to provide a new idea for explaining why TROAP affects the prognosis of STS." (PMID 37731946, 2023). "We observed that TROAP was upregulated in most types of tumor tissues." (PMID 37731946, 2023). "Considering that the number of tumor mutation burdens (TMB) and microsatellite instability (MSI) are essential indicators for predicting immune efficacy, we explored the association between TROAP, TMB, and MSI." (PMID 37731946, 2023). "After 20 days of tumor implantation, TROAP silencing significantly reduced tumor growth." (PMID 37127623, 2023). "Additionally, knockdown of TROAP reversed these inhibitory effects of METTL14 on tumor cell proliferation." (PMID 35251990, 2022). "TROAP expression was significantly correlated with tumor grade in the five cancer types." (PMID 36419876, 2022). "The expression of TROAP increased as the clinical and tumor stages increased." (PMID 36419876, 2022). "In addition, aberrant TROAP expression was associated with ESTIMATE score, MSI, TMB, and tumor immune microenvironment in cancers." (PMID 36419876, 2022). "Also, TISIDB was used to investigate the relationship between TROAP expression and tumor microenvironment(TME) among different cancer types." (PMID 36419876, 2022). "In transwell and wound healing assays, TROAP knockdown reduced tumor cell migration ability." (PMID 36419876, 2022). "The miR-519d-3p was reported to be a tumor suppressor by targeting TROAP in CRC cells." (PMID 32796815, 2020).